TLR7 (toll like receptor 7)
Diseases named in the same sentence as TLR7 in open-access papers (continued):
Sharing a sentence is not in itself a finding about the gene and the disease.
COVID-19 (continued). "MicroBeads selected CD4+ T cells, CD8+ T cells, and CD14+ monocytes from PBMCs were treated with plasma exosomes from early-stage COVID-19 patients and non-COVID donors for 16 h at 37 °C, followed by flow cytometry for expression of TLR3, TLR7, TLR8, and TLR9 gating on live cells." (PMID 36526691, 2022). "Conversely, based on a standardized functional immune-assay, we found that patients with severe pneumonia (whether COVID-19-related or not) displayed severe alterations of T-cell functionality on ex vivo CD3 and TLR7/8 stimulation." (PMID 33272291, 2020). "We found that the TLR-7 agonist, Resiquimod, and the TLR-4 ligand, LPS, induced significantly better IFNα and IFNγ responses in the later phase (day 28) of SARS-CoV-2 infection in those non-hospitalized COVID-19+ individuals as compared to early infection (day 0 and day 7)." (PMID 38543837, 2024).
Autoimmunity (184 papers, 2008 to 2026). The occurrence of an immune reaction against the organism's own cells or tissues. "TLR7 is essential for the activation of RNA-associated IC because TLR7 recognizes ssRNA essential for host defense against the development and progression of diseases caused by autoimmunity such as SLE." (PMID 39000140, 2024). "Mice with the orthologous Tnip1 mutation develop spontaneous autoimmunity associated with impaired mitophagy and autophagic silencing of proteins downstream of Toll-like receptor 7 signaling." (PMID 39060650, 2024). "Prior studies by our group have demonstrated that Tlr7 agonism accelerates disease in female pSD mice and drives expansion of age-associated B cells (ABCs), a B cell subset that mediates autoimmunity." (PMID 39310226, 2024). "Mice with this Unc93b1D34A mutation develop TLR7-dependent autoimmunity, suggesting that UNC93B1 carefully tunes levels of TLR7 to avoid responses to self-RNA." (PMID 38780621, 2024). "A recent study also revealed that such a variant increased the affinity of TLR7 for guanosine and cGMP and caused B-cell driven autoimmunity." (PMID 36677692, 2023). "Overexpression of TLR7 is known to induce autoimmunity and recently, a de novo TLR7 mutation was found to cause a monogenic form of the disease in a young individual." (PMID 37346043, 2023). "Genes associated to autoimmunity are also found on the X chromosomes, such as the expression of TLR-7, which has described in relation to lupus-associated autoimmunity." (PMID 37511278, 2023). "Evidence from mice with overexpression or deficiency of TLR7 further demonstrates a critical involvement of TLR7 signaling in autoimmunity." (PMID 36220996, 2022). "Deficiency of MyD88 (an adaptor protein downstream of TLR7) rescued autoimmunity, aberrant B cell survival, and all cellular and serological phenotypes." (PMID 35477763, 2022). "The authors used synthetic inhibitors of PNP to clarify the pathway through which PNP deficiency is toxic to developing T cells and also propose a mechanism for the association of PNP deficiency with autoimmunity through effects on TLR7." (PMID 35968787, 2022). "Functional evidence of a role for guanosine in regulating TLR7 signaling in humans was provided by the identification of a gain-of-function TLR7 mutation that enhances guanosine ligand affinity and promotes autoimmunity." (PMID 35653193, 2022). "Mice with T cell–specific PPP2R2D deficiency display less systemic autoimmunity when exposed to a TLR7 stimulator." (PMID 32897879, 2020). "Most recently, abnormal maintenance of X inactivation, with TLR7 escape, was implicated in autoimmunity." (PMID 31998321, 2019). "Increased function of TLR-7 causes an increment in spontaneous GC formation and an autoimmunity phenotype." (PMID 29556239, 2018). "The divergent roles played by TLR7 and 9 in autoimmunity are reflected in the variation seen in TLR7/9 polymorphisms and their subsequent effect on disease progression." (PMID 23227085, 2012). "To test the hypothesis that NOX2 regulates SLE by dampening TLR7-mediated autoimmunity, we crossed globally Tlr7-deficient mice with global Cybb-KO mice on the MRL.Faslpr SLE-prone background." (PMID 39042716, 2024). "Therefore, the rational design of antagonist ligands is a primary focus for the management of autoimmune disorders, cancers, virus infection, and other potential TLR7-associated clinical disorders." (PMID 36677692, 2023). "Imiquimod is a toll-like receptor 7 agonist that induces cellular apoptosis and recruits pro-inflammatory cytokines including tumour necrosis factor-alpha and interferon-alpha, which have been implicated in autoimmunity." (PMID 37025248, 2023). "Seminal studies revealed that self-derived ligands also activate TLR7, including RNA-associated immune complexes and U11 small nuclear RNA (U11snRNA), and this ability to recognize self-derived moieties underlies its pivotal role in autoimmunity." (PMID 36591307, 2022).
Autoimmunity (continued). "B cell–intrinsic TLR7 signaling and IL-6 production promote the development of spontaneous germinal centers (GCs) in secondary lymphoid tissues, which are associated with autoinflammation and autoimmunity." (PMID 35653193, 2022). "We therefore asked whether excess TLR7 would induce GCs and pathogenic autoimmunity in Sle1 TNF–/– mice by introducing the Yaa locus that codes for an extra copy of TLR7 on the Y chromosome." (PMID 35104241, 2022). "Even within mouse strains differences can be observed: e.g. some strains have a Y chromosome gene known as Yaa (y accelerated autoimmunity) which has resulted from a translocation of the gene encoding Toll-like receptor 7 (Tlr7) from the X chromosome onto the Y chromosome." (PMID 36518769, 2022). "Thus, higher TLR7 expression and signaling in women than in men can predispose women to SS, and in part explain the sex bias in autoimmunity." (PMID 36389822, 2022). "Together these studies identify a previously unappreciated pathogenic role for TLR7 in lacrimal gland autoimmunity and T1D development in male NOD mice adding to the growing body of evidence supporting sex differences in mechanisms of autoimmune disease in NOD mice." (PMID 33322152, 2020). "Differential methylation of genes PIK3AP1 and SPON2 is not reported in association with other similar autoinflammatory diseases; however, PIK3AP1 was associated with autoimmunity, and its increased expression was shown to promote TLR7-driven lupus-like disease." (PMID 32793186, 2020). "Our experiments evaluated the neurodevelopmental outcomes of heightened TLR7 signaling during gestation, based on the established role of TLR7 signaling in autoimmunity and accumulating evidence for associations between autoimmune disorders and neuropsychiatric disorders." (PMID 30610201, 2020). "564Igi BM chimeras in which the recipient FDCs were TLR-7-deficient exhibited less autoimmunity." (PMID 29556239, 2018). "Furthermore, altered TLR7 expression levels are implicated in various autoimmune disorders, indicating a key role for this receptor in modulating inflammation." (PMID 28928743, 2017). "Thus, we propose that monocytes (and DCs) contribute to the pathogenesis of STAT1 GOF-associated autoimmunity, which may be at least partly driven by the TLR7/8 hyperresponsiveness to self-nucleic acids." (PMID 36172362, 2022). "Crucially, rare TLR7 and TLR8 mutations at this antagonist binding site decrease inhibition by 2'-OMe guanosine RNA fragments, leading to autoimmunity in patients." (PMID 41667621, 2026). "emphasized the pathogenic involvement of STING and its downstream interferon responses in TLR7-driven autoimmunity, vascular injury, and AS." (PMID 40574833, 2025). "Reported gene variants increase the receptor's affinity for guanosine, leading to hypersensitive TLR7 signaling and enhanced B cell survival, finally contributing to B cell–mediated autoimmunity." (PMID 39964335, 2025). "In this study, we show that TASL and its newly identified paralogue TASL2 play a central role in endosomal TLR7/9-induced responses in vivo, affecting both antiviral immune and autoimmune SLE models." (PMID 39856058, 2025). "For example, evidence for a direct link between gene escape and female-biased autoimmunity has been demonstrated for TLR7 and TLR8, with their higher escape gene dose leading to enhanced immune responses." (PMID 40312568, 2025). "The miRNA-mediated TLR7/8 activation is relevant not only to immune response but also to neurodegeneration, cancers, autoimmunity, and various other diseases." (PMID 40329535, 2025). "This can lead to the development of novel therapeutic strategies targeting TLR7-related pathways in various diseases, including autoimmune disorders and infections." (PMID 40329535, 2025). "The major importance of TLR7 in the break of immune tolerance is strengthened by the independent discovery that several genetic/epigenetic variations in TLR7 leads to autoimmunity." (PMID 38571942, 2024).
Autoimmunity (continued). "The mechanism behind the development of autoimmunity was found to be reduced ability of TLR8 to regulate TLR7 signaling, as well as increased binding of TLR8 to TLR7 ligands, which increased TLR7 signaling." (PMID 38791389, 2024). "An important component of our work is that we identify a mechanism by which NOX2 curtails autoimmunity — NOX2 reduces inflammation by selectively regulating TLR7." (PMID 39042716, 2024). "Toll‐like receptor‐7 (TLR7) activation promotes autoimmunity, and metabolic syndrome (MetS) is a common comorbidity in patients with autoimmune disease." (PMID 38346802, 2024). "generated TLR8-deficient mice through gene targeting and revealed that mouse TLR8 plays a pivotal role in the regulation of mouse TLR7 expression and the spontaneous autoimmunity." (PMID 39544932, 2024). "Numerous studies have implicated TLR7 as the main driver of SLE disease, while both TLR8 and TLR9 have been shown to have more regulatory roles where they contribute to dampening TLR7 signaling and thereby prevent autoimmunity." (PMID 38791389, 2024). "It is also important to note that TLR7-driven CD11c+ B cells are enhanced in autoimmune-prone mice and enriched in individuals with autoimmunity." (PMID 36508037, 2023). "For the management of autoimmune disorders, several studies report the use of synthesized oligonucleotides to act as immunosuppressor of TLR7." (PMID 36677692, 2023). "Recent findings suggest that differences in subcellular sorting by Unc93b1 and syntenin-1 differentiate an autoimmunity promoting function of TLR7 from the protective effects of TLR9 in murine models." (PMID 36648888, 2023). "The observations that TLR7-driven autoimmunity was accelerated by B cell-specific Fcrl5 overexpression in mice and that TLR7/9-mediated B cell activation was facilitated by Fcrl5 cross-linking are consistent with many previous findings." (PMID 37841260, 2023). "ABCs are known to drive autoimmunity, are enriched for autoantibody specificities, are efficient antigen presenters, and require TLR7 or TLR9 signaling for formation in vitro." (PMID 37606042, 2023). "Overall, TLR8- or TLR9-deficiency decreases the competition with TLR7 for association with UNC93B1 and results to increased TLR7 trafficking and signaling that ultimately leads to autoimmunity." (PMID 36389822, 2022). "Nevertheless, our studies on TLR8-deficient mice revealed that TLR8 has an important function on restraining TLR7 and protecting from autoimmunity." (PMID 36389822, 2022). "There are also many genes of relevance to immune function and susceptibility for autoimmunity located on the X chromosome, including those encoding IL2-Rγ, IL13-Rα, CXCR3, CD40 ligand, TLR7 and TLR8, TIMP1 and Bruton’s tyrosine kinase (BTK)." (PMID 36518769, 2022). "Increased numbers of Ly6Chi cells in lymphoid organs are likely to be related to the induction of autoimmunity as previously reported for monocyte-derived DC (moDC) during Tfh induction, a mechanism mediated by the stimulation of TLR7 expressed by moDC." (PMID 35371102, 2022). "We conclude that TLR7 GOF can cause B-cell-driven autoimmunity including SLE due to increased affinity to guanosine, leading to a lowered threshold for TLR7 activation." (PMID 35477763, 2022). "TLR7 detects viral RNA and can also be inappropriately activated by self-RNA, generating autoimmunity." (PMID 35996406, 2022). "The importance of this regulation is reflected by the fact that deletion of TLR8 or/and TLR9 in mice or even diminution of TLR8 expression in humans, leads to increased TLR7 signaling and subsequent autoimmunity." (PMID 36389822, 2022). "We also assayed the effects of TLR7 agonism and IL-21 stimulation of LCLs on cell proliferation and the induction of plasma cells, both of which are characteristics of atMBCs in autoimmunity." (PMID 36248899, 2022).
Autoimmunity (continued). "Nonetheless, HFD-feeding provides an environment of increased adiposity and hyperleptinemia, allowing further study of interactions between obesity and TLR7-mediated autoimmunity." (PMID 35874527, 2022). "These include experimental autoimmune encephalitis, DNase II deficiency and TLR7-mediated lupus nephritis mouse models, indicating that type I IFN-independent pathways contribute to the autoimmunity at certain autoimmune conditions." (PMID 34819357, 2022). "Expression of tlr on mouse FDCs has been shown by immunohistochemistry (tlr4) and functionally in a tlr7 knock-out mouse model of autoimmunity." (PMID 34424268, 2021). "TLR7 participates in the maintenance of autoimmunity in the pathogenesis of experimental autoimmune encephalomyelitis in mice." (PMID 34394755, 2021). "These experiments show that the gut microbiome metabolic product TMAO increases TLR7 induced autoimmunity and vascular dysfunction." (PMID 35052589, 2021). "Consistent with this notion we have demonstrated the essential role of B cell intrinsic IFNγ signaling in autoreactive B cell development in TLR7-promoted SLE-autoimmunity." (PMID 32849556, 2020). "In light of the reported results, we proposed a novel role of EVs’ miRNAs in the etiology of T1D, suggesting the immune response modulation via the TLR7/8 activation and EVs miRNAs involvement into inflammation and autoimmunity." (PMID 32296701, 2020). "To determine the fate of B10 cells during TLR7 driven autoimmunity, we examined the viability and apoptosis of B10 and non-B10 cells in Sle1b, Sle1bYaa, and Sle1b.TLR7−/− mice at 3 months of age." (PMID 32849556, 2020). "One key unanswered question that remains is what TLR7 ligands trigger the TLR7 response in lacrimal glands in the context of SS-like autoimmunity." (PMID 33322152, 2020). "We created a Tlr7 knockout NOD mouse strain and performed histological and gene expression studies to characterize the effects of TLR7 on autoimmunity development." (PMID 33322152, 2020). "The p.Pro480Thr variant is predicted to affect the C-terminal tail of the UNC93B1 that has recently been shown to restrict TLR7 mediated autoimmunity via an interaction with syndecan binding protein (SDCBP)." (PMID 32028618, 2020). "Several investigations showed that murine TLR8 plays a pivotal role in the regulation of myeloid cells and prevention of autoimmunity, by controlling TLR7 expression." (PMID 32854231, 2020). "The purpose of this study was to define the role of TLR7 in the spontaneous development of SS-like autoimmunity in NOD mice." (PMID 33322152, 2020). "Tlr7 duplication and translocation in the Yaa mouse model reveals the importance of supplementary genetic material from the X Chr in triggering autoimmunity." (PMID 31501466, 2019). "Previous data from a number of groups has shown that TLR7 plays a critical role in the initial stages of autoimmunity and development of ANAs." (PMID 31354711, 2019). "Although we found that TLR7-stimulated NZM2410 mice had both accelerated autoimmunity and nephritis, like B6, treated NZM2410 mice also succumbed from non-nephritis complications." (PMID 31998321, 2019). "Taken together these findings indicate that the autoimmunity observed across multiple model systems is dependent on a TLR7, MyD88-IRAK4 kinase, and IRF5 dependent signaling cascade, which is independent of NFkB nuclear translocation and cytokine production." (PMID 31354711, 2019). "For instance, Tlr7 expression is increased in Tlr8 null mice and these mice exhibit lupus-like autoimmunity due to increased levels of RNP-specific autoantibodies." (PMID 31684953, 2019). "Obviously, TLR9 and TLR7 normally compete for endosomal trafficking implying that increased TLR7 signaling driving autoimmunity can outweigh the pro-inflammatory effects of TLR9." (PMID 29650017, 2018). "Conversely, increased expression of TLR7 in transgenic mice overexpressing TLR7 spontaneously developed fatal and acute immune dysregulation and autoimmunity." (PMID 30402506, 2018).